SMAD3 (SMAD family member 3)
Diseases named in the same sentence as SMAD3 in open-access papers (continued):
Sharing a sentence is not in itself a finding about the gene and the disease.
ascending aortic dilatation (1 paper, 2022). "Specific to ascending aortic aneurysms associated with AV malformations, however, SMAD3 may be a promising target." (PMID 36104385, 2022). "Our findings reveal that SMAD3 may be a superior therapeutic target against ascending aortic dilatation in general, and maybe even more so in individuals with AV disease." (PMID 36104385, 2022). "Therefore, SMAD3 should be further investigated as a therapeutic target against ascending aortic dilatation in general, and particularly in BAV/UAV patients." (PMID 36104385, 2022).
astrocytic tumor (1 paper, 2025). A glial tumor of the brain or spinal cord showing astrocytic differentiation. "Figure 2illustrates the promoter methylation status of six genes involved in the TGF-β signaling pathway—SKIL, SMAD1, SMAD3, SMAD4, BMP2, and MAPK1—across astrocytic tumors of increasing malignancy (grades G2, G3, and G4)." (PMID 40869118, 2025). "Elevated expression of SMAD1, SMAD3, and SKIL emerged as strong prognostic indicators, underscoring their potential as biomarkers and therapeutic targets in astrocytic tumors." (PMID 40869118, 2025).
astrocytomas (1 paper, 2025). "Compared to G2 tumors, high-grade astrocytomas (G3 and G4) exhibited elevated levels of SKIL, SMAD1, SMAD3, BMP2, and MAPK1, with most differences reaching statistical significance (p < 0.05)." (PMID 40869118, 2025). "In this study, we present multi-level evidence demonstrating that key mediators of the TGF-β signaling pathway—SKIL, BMP2, SMAD1, SMAD3, SMAD4, and MAPK1—are consistently upregulated in high-grade astrocytomas." (PMID 40869118, 2025).
atopic dermatitis (1 paper, 2024). "Interestingly, reports suggested that the Smad3 pathway can regulate allergen-induced skin inflammation and systemic IgE antibody production in a mouse model of atopic dermatitis, indicating that the Smad3 signaling pathway may be a key signaling target in allergic skin diseases." (PMID 38577622, 2024).
Barrett adenocarcinoma (1 paper, 2017). An adenocarcinoma arising from Barrett metaplastic epithelium in the esophagus. "Our findings are consistent with previous findings that BMP7 is shown to induce phosphorylation of Smad2/3 in Barrett’s adenocarcinoma cells and that BMP7 stimulates Smad3 target CAGA box promoter activity to a similar extent to that induced by TGF-β in a mammary epithelial cell line." (PMID 27696331, 2017).
basal cell carcinoma (1 paper, 2023). A carcinoma involving the basal cells. "The regulatory network also showed that DEGs including LEF1, FZD3, SMAD3, and BMP4 were important regulators of the Wnt signaling, basal cell carcinoma, and Hippo signaling pathways." (PMID 36979137, 2023).
biliary atresia (1 paper, 2022). A rare, biliary tract disease characterized by progressive obliterative cholangiopathy of the intra- and extrahepatic bile ducts, occurring in the embryonic/ perinatal period, leading to severe and persistent neonatal jaundice and acholic stool. "We then screened all genes contributing to TGFβ signaling in these two data sets of biliary atresia and confirmed that SMAD3 played an important role in both data sets." (PMID 36090996, 2022).
brain hemorrhage (1 paper, 2015). "Collectively, these results reveal that a precise balance of TGFβ signaling is essential for normal control of angiogenesis, with abnormally high or low levels of Smad3 activation in endothelial cells leading to similar defects in blood vessel sprouting and brain hemorrhage." (PMID 26586223, 2015).
carotid atherosclerosis (1 paper, 2024). A thickening and loss of elasticity of the walls of carotid arteries that occur with formation of atherosclerotic plaques. "The aim of our study was to investigate the association between the rs17228212 polymorphism of the SMAD3 gene and advanced carotid atherosclerosis in Slovenian subjects." (PMID 38791063, 2024). "In the endarterectomy sequesters from surgically treated patients with advanced carotid atherosclerosis, there was an increase in the numerical areal density of SMAD3-positive cells in subjects with the T allele in comparison to those with the C allele (41 ± 6/mm2 versus 25 ± 4/mm2; p < 0.001)." (PMID 38791063, 2024). "The aim of our study was to investigate the association between the rs17228212 polymorphism of the SMAD3 gene and advanced carotid atherosclerosis in Slovenian subjects and to investigate the effect of the rs17228212 SMAD3 polymorphism on the expression of SMAD3 in endarterectomy sequesters." (PMID 38791063, 2024).
cartilage tumours (1 paper, 2017). "A high ratio of p-SMAD3 (or p-SMAD2)/PEG10 may be a determinant for cartilage tumours to gain malignancy." (PMID 29044189, 2017). "First, p-SMAD3 and p-SMAD1/5 accumulated in nuclei of chondrosarcoma cells, whereas PEG10 was abundantly expressed in enchondroma cells, indicating that expression of PEG10 and activated R-SMADs were mutually exclusive between these benign and malignant cartilage tumours." (PMID 29044189, 2017).
cataract (1 paper, 2009). Partial or complete opacity of the crystalline lens of one or both eyes that decreases visual acuity and eventually results in blindness. "Moreover, TGFβ-induced apoptosis of lens epithelial cells, another feature of subcapsular cataracts (see Introduction), was shown to be significantly enhanced in Smad3 knockout mice." (PMID 19421408, 2009).
chondrosarcoma (1 paper, 2017). A malignant cartilaginous matrix-producing mesenchymal neoplasm arising from the bone and soft tissue. "We analysed seven enchondromas, and 11 grade 1 and seven grade 2 chondrosarcomas to evaluate the activity of SMAD3 and SMAD1/5." (PMID 29044189, 2017). "Here, we found highly active transforming growth factor-β (TGF-β) and bone morphogenetic protein (BMP) signalling in human chondrosarcomas compared with enchondromas by immunohistochemistry of phosphorylated SMAD3 and SMAD1/5." (PMID 29044189, 2017). "Our present study is the first to show differential activation of TGF-β R-SMAD (p-SMAD3) between enchondroma and low-grade chondrosarcoma." (PMID 29044189, 2017). "As positive controls, SB431542 and LDN193189 inhibitors completely abolished TGF-β1-induced SMAD3 phosphorylation and BMP-6-mediated activation of SMAD1/5/9, respectively, in both SW1353 and Hs 819.T chondrosarcoma cell lines (lanes 4–7 and 11–14)." (PMID 29044189, 2017).
chronic GVHD (1 paper, 2017). "Moreover, high level of Smad3 may correlate with low rates of both acute and chronic GVHD." (PMID 29088831, 2017).
ciliopathy (1 paper, 2022). A genetic disorder of the cellular cilia or the cilia anchoring structures, the basal bodies, or of ciliary function. "The targets of CREBP1 found from among the genes shared between the HLHS and ciliopathy interactomes were EP300, PRNP, SMAD3, SUMO1 and TBX6, while the targets of ALX4 were JUN and TCF7L2." (PMID 35456433, 2022).
co-infection (1 paper, 2023). "Further, this FoxO3-induced stimulation of MuRF-1 was completely reversed with Ad-Smad3 co-infection." (PMID 37693008, 2023).
colonic adenocarcinomas (1 paper, 2007). "More recently, colonic adenocarcinomas have been initiated in SMAD3-deficient mice that have been exposed to Helicobacter infection suggesting a causal association." (PMID 17498313, 2007).
colonic disease (1 paper, 2020). "Future studies should investigate whether measuring SMAD3 from ccfDNA is useful in the case of early colonic disease." (PMID 33036415, 2020).
colorectal adenocarcinoma (1 paper, 2020). The most common type of colorectal carcinoma. "Meanwhile, another study found the relation between expression of CEA (CEACAM5) gene and TGF-β pathway genes (TGFBR1, TGFBR2, and SMAD3) in colorectal adenocarcinoma cells." (PMID 33123542, 2020).
congenital contractural arachnodactyly (1 paper, 2024). Congenital contractural arachnodactyly (CCA, Beals syndrome) is a connective tissue disorder characterized by multiple flexion contractures, arachnodactyly, severe kyphoscoliosis, abnormal pinnae and muscular hypoplasia. "Genetic variants in genes including TGFBR1, TGFBR2, TGFB2, TGFB3, SMAD2, and SMAD3 result in Loeys–Dietz syndrome and are reported to cause Marfan-like phenotypes and variants in FBN2 and COL3A1 result in congenital contractural arachnodactyly and Ehlers–Danlos syndrome type IV." (PMID 38791509, 2024).
corneal diseases (1 paper, 2008). "TGF-β1 and SMAD3 may be involved in the pathology of corneal diseases associated with HSV-1 infection." (PMID 18776948, 2008). "Expression of TGF-β1 and SMAD3 in HSV-1 infected HCE cells decreased in this study, which suggested that they may be involved in corneal diseases that are associated with HSV-1 infection." (PMID 18776948, 2008).
corneal infection (1 paper, 2008). A viral or bacterial infectious process affecting the cornea. "The specific function of TGF-β1 and SMAD3 in HSV-1 corneal infection requires further investigation." (PMID 18776948, 2008). "The present study was undertaken to investigate whether transforming growth factor-β (TGF-β) isoforms (TGF-β1, TGF-β2, and TGF-β3) and SMADs (SMAD2 and SMAD3) are involved in herpes simplex virus type 1 (HSV-1) corneal infection." (PMID 18776948, 2008).
craniosynostosis (1 paper, 2023). Craniosynostosis is defined as the premature fusion of one or more cranial sutures leading to secondary distortion of skull shape resulting in skull deformities with a variable presentation. "The Amber genes included three variants in PRRX1 (which contributed towards the first experimental cohort of patients with craniosynostosis and variants in PRRX1, providing substantial evidence to promote this gene to Green), one splicing variant in SMAD3 (c.206+1G>A; p. ?" (PMID 36980886, 2023).
cystic kidney disease (1 paper, 2020). A congenital or acquired kidney disorder characterized by the presence of renal cysts. "SCLT1 deficiency has been linked with cystic kidney disease, and SMAD genes (including SMAD3) have been reported to affect CKD progression when they are dysregulated." (PMID 32386536, 2020).
dementia (1 paper, 2023). Loss of intellectual abilities interfering with an individual's social and occupational functions. "HF patients and MI mice exhibited increased TGF-β and SMAD3 phosphorylation levels that potentially play a role in cardiogenic dementia." (PMID 37429912, 2023).
dissection (1 paper, 2017). The separation and isolation of tissues for surgical purposes, or for the analysis or study of their structures. "Smad3 was significantly increased in vascular smooth muscle cells (VSMCs) treated by hypoxia and aortic tissue of thoracic aortic dissection (TAD) patients, which was consistent with that of OSA canines." (PMID 28465478, 2017).
dysplasia (1 paper, 2013). A usually neoplastic transformation of the cell, associated with altered architectural tissue patterns. "However, low grade dysplasia developed in the distal colon of 1/6 and 2/12 3%-DSS-treated Smad3+/− and WT mice, respectively, at the 17-week end point and 1/15 DSS-cycles treated Smad3+/− developed high grade dysplasia (grade 3) in the cecum." (PMID 24244446, 2013).
End Stage Liver Disease (1 paper, 2017). Final stage of a liver disease when the liver failure is irreversible and LIVER TRANSPLANTATION is needed. "Co-IP revealed that ERG interacts with SMAD3 in HUVEC and in Hepatic Sinusoidal Endothelial Cells (HSEC) isolated from transplant patients with end-stage liver disease." (PMID 29026072, 2017).
endometrial tumors (1 paper, 2023). "Given the TGFβ signaling pathway alterations found in human endometrial tumors, we generated mice with epithelial-specific inactivation of Smad225 and Smad315 using Ltf-cre26 (“Smad2/3 cKO” mice) to investigate the in vivo roles of SMAD2 and SMAD3 signaling in the luminal uterine epithelium." (PMID 36906706, 2023).
endothelial dysfunction (1 paper, 2013). In vascular diseases, endothelial dysfunction is a systemic pathological state of the endothelium (the inner lining of blood vessels) and can be broadly defined as an imbalance between vasodilating and vasoconstricting substances produced by (or acting on) the endothelium. "In conclusion, these data suggest that endothelial dysfunction can exacerbate renal interstitial fibrosis through increased fibroblast proliferation and collagen production via enhanced Smad3 linker phosphorylation." (PMID 24391884, 2013).
endotoxemia (1 paper, 2018). "For example, homozygous SMAD3 knockout mice had higher mortality in response to LPS-induced endotoxemia compared to wild-type mice." (PMID 30363688, 2018).
enteritis (1 paper, 2018). Inflammation of the small intestine. "There were more Foxp3+ Tregs and Smad3 and NFAT2 infiltrated into the duodenum after adoptive transfer of CD4+CD25+ Tregs, which was a significant difference relative to the enteritis group (p<0.05)." (PMID 30364052, 2018). "In this study, the expression of Smad3 and NFAT2 in the Treg-infusion group was significantly higher than that in the enteritis group, but the expression of Stat3 was lower than that in the enteritis group." (PMID 30364052, 2018).
enterocolitis (1 paper, 2022). An inflammatory process affecting the small intestine and colon. "We used immunohistochemistry to detect the expression characteristics of Smad3 and nuclear factor kappa B (NF-κB) proteins in human postnecrotizing enterocolitis stricture." (PMID 36474625, 2022).
esophageal adenocarcinoma (1 paper, 2014). A malignant tumor with glandular differentiation arising predominantly from Barrett mucosa in the lower third of the esophagus. "Because Smad3 was recently shown to interact with Notch1 in esophageal adenocarcinoma cells after treatment with TGF-β, we tested if N1ICD binding to the Sox9 promoter RBP-Jκ site was dependent on TGF-β signaling in lung ADC." (PMID 25004243, 2014).
familial aortopathy (1 paper, 2023). "SMAD3 has been well characterized to play a functional role in familial aortopathy." (PMID 36926042, 2023).
familial pulmonary arterial hypertension (1 paper, 2020). "Moreover, ALK5 mediates abnormal proliferation of vascular smooth muscle cells from patients with familial pulmonary arterial hypertension and is required for TGF-β-induction of smooth muscle cell differentiation markers through Smad3 and MAPK pathway." (PMID 32065217, 2020).
Fanconi anemia (1 paper, 2020). Fanconi anemia (FA) is a hereditary DNA repair disorder characterized by progressive pancytopenia with bone marrow failure, variable congenital malformations and predisposition to develop hematological or solid tumors. "In contrast, TGF‐β has also been shown to protect against genomic instability by enhancing nonhomologous end‐joining repair, ATM activity, and the SMAD3/β2spectrin/Fanconi anemia DNA repair pathway." (PMID 32073751, 2020).
female infertility (1 paper, 2022). Diminished or absent ability of a female to achieve conception. "Specifically, VDR is associated with female infertility, whereas CEBPB has been described as relevant factor for female reproduction for its role in ovarian follicle development, together with SMAD3 and ESR2." (PMID 36589743, 2022).
focal segmental glomerulosclerosis (1 paper, 2025). A renal disorder characterized by sclerotic lesions in the glomeruli. "FSP-1 has been shown to enhance fibrosis via TGF-β/Smad3 signaling, a pathway implicated in other CKDs, including IgAN, DN, and focal segmental glomerulosclerosis (FSGS)." (PMID 40141260, 2025).
gastric diseases (1 paper, 2020). "TGF-β-SMAD3 can inhibit CDK2 to promote Treg differentiation, which indicates that the immune microenvironment may play an essential role in the gastric diseases." (PMID 33282942, 2020).
gingival fibromatosis (1 paper, 2021). "The in vivo overexpression of Netrin-1 and COL6A as well as the nuclear accumulation of p-Smad-3 indeed supported the idea that aberrant TGFβ signaling may contribute in the pathogenesis of ERS gingival fibromatosis." (PMID 34777248, 2021).
hair loss (1 paper, 2026). "The authors concluded that miR-122-5p-loaded exosomes represent a novel therapeutic strategy for treating DHT-induced hair loss, with the potential to reverse AGA progression by targeting TGF-β1/SMAD3 signaling (Level V)." (PMID 41561359, 2026).
HCMV infection (1 paper, 2021). "In this study we show that SMAD3, a TGFβ receptor-associated SMAD, cooperates with IRF7 to induce type I IFNs during HCMV infection, highlighting a unique interconnection between TGFβ and IFN signaling." (PMID 34411201, 2021). "In this study we show that SMAD3, a TGFβ receptor-associated SMAD, cooperates with IRF7 to induce type I IFN during HCMV infection." (PMID 34411201, 2021). "Lytic HCMV infection induces the production of TGFβ, which binds to the TGFβ receptor and activates the receptor-associated SMAD SMAD3." (PMID 34411201, 2021). "This study uncovers a novel link between SMAD3 and IRF7 in the induction of type I IFNs, highlighting the crosstalk between TGFβ and innate immune signaling during HCMV infection." (PMID 34411201, 2021). "In order to assess the role of miR-UL22A regulation of SMAD3 and IRF7-mediated signaling in the context of HCMV infection, we next tested the induction of IFN transcripts following infection with WT and ΔmiR-UL22A mutant viruses in tHF and ΔIRF7 cells." (PMID 34411201, 2021). "Together, these data support the hypothesis that SMAD3 and IRF7 cooperate to induce IFN production during HCMV infection, which has negative effects on viral replication." (PMID 34411201, 2021).
HELLP syndrome (1 paper, 2023). A life-threatening condition that can potentially complicate pregnancy. "The expression of IGFBP-3 is elevated in HELLP syndrome, which may subsequently promote cell apoptosis by affecting the expression and function of IGF-1, VEGF, and TGFβ1 in the IGF/PI3K/Akt, TGF-β1/Smad3, and VEGF/eNOS/NO pathways." (PMID 37950229, 2023).
hepatitis C (1 paper, 2020). "We performed immunohistochemistory using domain-specific phospho-Smad3 Abs in liver biopsy specimens from 30 NASH patients representing different fibrotic stages and 20 chronically infected hepatitis C patients as controls." (PMID 31991602, 2020). "We immunohistochemically examined domain-specific Smad3 phosphorylation in liver biopsy specimens from 30 NASH patients representing different fibrotic stages and 20 chronically infected hepatitis C patients as controls, correlating Smad3 phosphorylation with clinical course." (PMID 31991602, 2020).
hypercortisolism (1 paper, 2015). "The overall effects of these actions on myostatin, miR-27a, and SMAD3 would be difficult to predict at present, but these findings might be implicated in the pathogenesis of glucocorticoid-induced muscle atrophy characteristic for hypercortisolism." (PMID 26161091, 2015).
Hypoglycemia (1 paper, 2021). A decreased concentration of glucose in the blood. "SMAD3 was higher at 1 h and 2 h post-hypoglycemia in T2D compared to control (4696.5 ± 371.1 vs 3870.1 ± 132.0, 1 h post-hypoglycemia, p < 0.05; 5369.6 ± 245.5 vs 4545.1 ± 211, 2 h post-hypoglycemia, p < 0.05)." (PMID 34426634, 2021). "In control subjects, HSPB1, SMAD3 and HSPA1A decreased significantly, whilst MAPKAPK5 increased significantly in controls from baseline to hypoglycemia whilst, in T2D, PPP3CA increased and EPHA2 decreased." (PMID 34426634, 2021).
hypoplastic left heart syndrome (1 paper, 2014). Hypoplastic left heart syndrome (HLHS) refers to the abnormal development of the left-sided cardiac structures, resulting in obstruction to blood flow from the left ventricular outflow tract. "This is the first case report of a SMAD3 mutation in a patient with hypoplastic left heart syndrome." (PMID 24711937, 2014). "We present a 14-year-old boy born with hypoplastic left heart syndrome (HLHS) who developed significant aneurysm of the neoaorta and proximal arch after completed, staged palliation and who was found to have a novel, pathogenic SMAD3 mutation." (PMID 24711937, 2014).